RNU1-20P (RNA, U1 small nuclear 20, pseudogene)
Gene: Small nuclear RNA gene on chromosome 3 (192,729,555 to 192,729,716, reverse strand). Ensembl gene ENSG00000200184.
Homologues: Orthologues: macaque U1 (88% identical), chimpanzee U1 (85% identical), rabbit U1 (67% identical), dog U1 (54% identical). Paralogues in human: RNU1-1 (83% identical), RNU1-2 (83% identical), RNU1-27P (83% identical), RNU1-28P (83% identical), RNU1-3 (83% identical), RNU1-4 (83% identical), RNVU1-18 (83% identical), RNVU1-29 (83% identical), U1 (83% identical), RNVU1-28 (83% identical), RNVU1-31 (83% identical), RNVU1-7 (83% identical), and 134 more.